ARG1 (arginase 1)
Diseases named in the same sentence as ARG1 in open-access papers (continued):
Sharing a sentence is not in itself a finding about the gene and the disease.
colitis (continued). "We have identified distinct roles of IL-17A and IL-17F in modulating DSS-induced colitis in mice and we demonstrated the benefit of quercetin in colitis dependent on Arg-1 secreted by MDSC after ESR/STAT3 activation." (PMID 32391010, 2020). "In the present study, we demonstrated that Arg-1 deletion in myeloid cells promoted DSS-induced colitis progression via decreases in the MDSC and TH17 cell populations." (PMID 32391010, 2020). "Treatment with T. spiralis AES significantly increased macrophage expression of CD206 and Arg-1 and simultaneously attenuated colitis severity." (PMID 33117347, 2020). "Together, these results indicated a central role of MDSC-derived Arg-1 in alleviating immune response during acute colitis." (PMID 32391010, 2020). "IL-17A expressed by TH17 cell increased obviously in PP and mLN, whereas IL-17F levels decreased in the presence of high levels of MDSC-derived Arg-1, proving once again that TH17 cell polarization is facilitated by Arg-1 expressed by MDSC during colitis." (PMID 32391010, 2020). "Together, these findings demonstrate a protective role of MDSC-derived Arg-1 during colitis after activates ESR/STAT3 signaling in MDSC." (PMID 32391010, 2020). "In conclusion, we have demonstrated distinct roles of IL-17A and IL-17F in DSS-induced colitis mice model which was dependent on increased Arg-1 secreted by MDSC after ESR/STAT3 activation." (PMID 32391010, 2020). "The induced M2 macrophages have shown therapeutic potential in chemical-induced colitis, partially by producing IL-10 and arginase-1." (PMID 29774026, 2018). "The expression levels of CD206, Arg1, Fizz1, and Ym1 (well-known M2 macrophage markers) were decreased or slightly increased in the colons of colitis model mice treated with PBS." (PMID 28701721, 2017). "Using this protein during experimental colitis caused a Th2 immune response that correlates to reduced inflammation and the enhanced expression of the AAM markers Arg-1, FIZZ-1, TGF-β, and IL-10." (PMID 27648452, 2016). "It has also been noted previously, that thatthe majority of MDSCs present at the sites of colitis, express ARG1 while expressingminimal levels of iNOS41." (PMID 26848037, 2016). "Finally, immunofluorescence analysis of iNOS and arginase-1 protein expression in the colon confirmed that DSS-induced colitis promoted iNOS expression, which was reduced by TcES treatment, while arginase-1 expression increased." (PMID 40576745, 2025). "Notably, KO mice had a significant increase in Arginase 1 expression in mucosal fibroblasts compared with other colitis model groups, showing the possible interaction between transplanted macrophages and fibroblasts." (PMID 40761793, 2025). "It was observed that iNOS levels increased while Arg1 levels decreased during colitis." (PMID 38774206, 2024). "Furthermore, the high dose of CYN enhanced the alternative activation of peritoneal macrophages isolated from colitis mice, as shown by the increased expression of IL-4 and Arg1." (PMID 36278202, 2022). "Moreover, the expression of Arg1 in colonic macrophages was markedly reduced in DRD5−/− mice during colitis." (PMID 34001860, 2021). "Elevated Arg-1 enhanced IL-17A expression but decreased IL-17F levels and contributed to attenuating immune response in the colorectum, thereby maintained intestinal barrier integrity and ultimately alleviating colitis." (PMID 32391010, 2020). "Indeed, ACT1 expression was elevated to various degrees in colitis mice, whereas IL-22 level was decreased upon arg-1 deletion during colitis." (PMID 32391010, 2020). "Indeed, decreased Arg-1 aggravates DSS-induced colitis, presence of Arg-1 attenuate DSS-induced colitis." (PMID 32391010, 2020). "Similarly, exosomes with enzymatically active ARG1 that were isolated from granulocytic MDSCs of tumor-bearing mice attenuated DSS-induced murine colitis by suppressing Th1 cells and promoting Treg differentiation." (PMID 31278254, 2019).
colitis (continued). "Indeed, M2-associated genes (Arg1, IL-10, Fizz1, and Mrc1) were increased and M1-associated genes (IL-1β, IL-6, IL-12, and TNF-α) were decreased in colons of DSS colitis miR-155−/− mice." (PMID 29774026, 2018). "Reactivation of quiescent colitis was associated with a significant increase in an M2 macrophage marker [Arginase 1 (Arg1)], but not Chitinase-like 3 (Ym1) expression, and hCTS treatment (1.5 mg/kg/day, 7 days, i.r)." (PMID 28871257, 2017). "ARG1 has a protective role inmurine colitis by competitive inhibition of iNOS36." (PMID 26848037, 2016). "During experimental colitis, it has been shown that T. crassiceps infection induces the expression of Arg-1, YM-1, and FIZZ-1, which is related to increased collagen deposition in the intestine that does not cause fibrosis but diminishes intestinal inflammation and hemorrhage." (PMID 27648452, 2016). "Taken together, these results strongly support the hypothesis that G-MDSC exo could attenuate DSS-induced murine experimental colitis and suggest that Arg-1 plays an important role in this process." (PMID 26885611, 2016). "However, PMN-MDSC exosomes could transport Arg-1 and facilitate the spontaneous improvement of colitis via a similar immunoregulatory pathway." (PMID 37733169, 2024). "In addition, increased ARG1 levels areresponsible for the suppressive mechanisms mediated by different subsets of MDSCs,which have been described in animal models of experimental colitis and humanIBD11." (PMID 26848037, 2016). "Taken together, these data showed that butyrate-treated mice have reduced clinical disease and histological damage compared with control mice, and this protection during DSS-induced colitis may correlate with increased in Arg1 protein expression in the colon during inflammation." (PMID 27094081, 2016). "In DSS colitis, the activation of estrogen receptors increased MDSC-derived ARG1 and consequently alleviated colitis." (PMID 40244120, 2025). "Genes representative of anti-inflammatory macrophage polarization (Mrc1, Hmox1, Arg1 and Chi3l3) were either unchanged or downregulated by MSC treatments in contrast to some reports in acute chemically-induced colitis models." (PMID 38503815, 2024). "Nevertheless, BM-MSC treatments downregulated Nos2, Arg1, Gata3, Mrc1 and Hmox1 which were upregulated in Winnie mice and IBD patients; but are reportedly also upregulated by MSCs in chemical models of colitis." (PMID 38503815, 2024). "Recent studies revealed that AW ESA significantly upregulated the expression of CD206 and Arg-1 in macrophages and attenuated DSS-induced murine colitis by activating M2 macrophage polarization." (PMID 37705099, 2023). "Western blotting revealed reduced expression of HMGCS2, ARG1, and CD206 and increased expression of iNOS and CD86 in colon tissues from the mouse models of DSS-induced colitis, further validating these findings." (PMID 38633005, 2023). "Due to the presence of high levels of arginase-1 (Arg-1) in MDSC-Exo, these exosomes suppress inflammatory responses and help treat induced colitis in mice by reducing the number of Th1 cells and increasing Treg." (PMID 35550636, 2022). "Within the context of helminth-therapy for colitis, we noted increased expression of colonic FIZZ1 and arginase-1 mRNA, markers indicative of an M(IL4); however, these markers are not exclusive to M(IL4)s." (PMID 34691050, 2021). "Quercetin effectively stimulated MDSC in DSS-induced colitis mice by activating ESR/STAT3, accompanied by higher Arg-1 and iNOS production." (PMID 32391010, 2020). "High level of Arg-1 facilitates TH17 cell polarization and enhances IL-17A expression but inhibits IL-17F level in the colorectum during colitis." (PMID 32391010, 2020). "High level of Arg-1 favors accumulation of IL-17A, but reduced IL-17F expression in the colorectum of mice and ultimately leading to relief of colitis, indicating a potential clinical impact of MDSC-derived Arg-1 for controlling inflammatory bowel disease." (PMID 32391010, 2020).
colitis (continued). "Collectively, these findings revealed that Arg-1 deletion resulted in decreases in the MDSC population and MDSC suppressive factors expression during acute colitis." (PMID 32391010, 2020). "Quercetin treatment activated ESR signal in MDSC and in turn boosted STAT3 phosphorylation, dramatically increased MDSC percentage and up-regulated Arg-1 and iNOS in MDSC during colitis." (PMID 32391010, 2020). "Intraperitoneal injection of the Arg-1 inhibitor nor-NOHA effectively alleviated mouse colitis progression." (PMID 32391010, 2020). "As expected, Fgl2-deficient colonic macrophages isolated from DSS-treated mice produced higher levels of the M1 effector molecule IL-1β, but lower levels of the M2 polarization markers MR, Arg-1, and Fizz1 in DSS colitis than macrophages from DSS-treated WT mice." (PMID 29441068, 2018). "Furthermore, the mRNA expression level of iNOS was significantly decreased and that of the M2 markers CD206, Arg1, Fizz1, and Ym1 were markedly increased in colon tissues of DSS-induced colitis mice infused with cAT-MSCs compared with PBS-treated mice." (PMID 29625582, 2018). "Inhibition of Arg-1 activity with nor-NOHA partly attenuated the improvement of DSS-induced colitis by G-MDSC exo." (PMID 26885611, 2016). "Thus, it is conceivable that the protectionof gp130757F/F mice from acute DSS-induced colitis is viamyeloid-specific STAT3 activation and expansion of immunosuppressive ARG1-expressingG-MDSC subsets in the colon." (PMID 26848037, 2016). "In a dextran sulfate sodium (DSS)-induced colitis model mice, LBP (intragastrica (i.g.), 200 mg/kg) could suppress the expression of the M1 macrophage marker nitric oxide synthase 2 (NOS2) while promoting the expression of the M2 marker arginase 1 (Arg-1)." (PMID 41050703, 2025). "Our results have shown that the absence of Arg-1 results in increased DAI score and poor prognosis in mice suffering DSS-induced colitis." (PMID 32391010, 2020).
Stroke (48 papers, 2016 to 2025). Sudden impairment of blood flow to a part of the brain due to occlusion or rupture of an artery to the brain. "Among these genes, such as Fabp5, Spp1, and Arg1, has been found in stroke-associated macrophages, foamy macrophages in atherosclerotic plaques, and lipid-associated macrophages in myocardial infarct." (PMID 40777042, 2025). "ARG1 has been implicated in promoting anti-inflammatory (M2) phenotypes and was linked to stroke severity." (PMID 38049831, 2023). "Our results suggested that Arg1+ microglia/macrophages’ deficiency exacerbated stroke-induced injury." (PMID 36361836, 2022). "A recent study showed that stroke-related immune suppression is associated with activated neutrophil and ARG1 release in middle cerebral artery occlusion (MCAO) mouse." (PMID 27672514, 2016). "ARG1, which was highly expressed in IS patients, is closely associated with macrophage polarization and may influence neutrophil recruitment and activation, further contributing to the inflammatory response seen in stroke." (PMID 39697434, 2024). "In an animal model, Cai discovered that ARG1 promotes microglia/macrophage cytomegaly and inflammation regression in stroke mice, thus contributing to brain tissue injury repair." (PMID 39697434, 2024). "The density of Arg1+ cells dramatically increased and reached a peak of 1011.5 ± 47.0 cells/mm2 on Day 5 after the stroke." (PMID 36361836, 2022). "We observed Arg1+ cells as early as one day after stroke at the lesion site and peaked on Day 5 after stroke." (PMID 36361836, 2022). "The expression of arginase 1 (Arg1), a key player in regulating nitrogen homeostasis, is altered in the peripheral circulation after stroke." (PMID 36361836, 2022). "After the depletion of Arg1+ microglia/macrophages, we found worse neurodegeneration and stroke outcome in mice." (PMID 36361836, 2022). "Arginase-1, a product of the M2 phenotype, was found to be highly elevated on days 3 and 5 in the previous stroke group, whereas its level remained low in the control group for the first 7 days." (PMID 35780249, 2022). "Since the effect of MCLs lasts for more than 48 h, it was the Arg1+ microglia/macrophages on the third and fourth day after stroke that were cleared." (PMID 36361836, 2022). "Endocytosis of STAT6/ARG1 can reduce inflammation and improve the outcome of stroke by regulating the phenotypes of macrophages/microglia." (PMID 36034287, 2022). "At present, it is reported that the expression of ARG-1 in the blood of patients with stroke is heightened, and its level is related to infarct size, implying the involvement of ARG in the mechanisms of post-hypoxic-ischemia." (PMID 34603484, 2021). "To better understand the impact of microglial depletion on the ischemic damage, we quantitated the cells expressing typical inflammatory molecules iNOS and Arg1 after stroke." (PMID 33757565, 2021). "Our data showed that ischemia caused extensive expression of pro-inflammatory molecule iNOS and anti-inflammatory molecule Arg1 on brain cells 3 days after stroke." (PMID 33757565, 2021). "The decrease mRNA levels of Arg-1 and IL-10 were markedly showed in stroke and stroke+PBS groups and less than that of the sham group (∗∗P < 0.01, ∗∗∗P < 0.001)." (PMID 32908485, 2020). "Increased amounts of splenic CD11b+Ly-6C+ Mo-MDSCs with upregulated arginase-I (Arg1) as a marker for an intact immunosuppressive capacity were reported in an experimental stroke model after 24 h." (PMID 33329318, 2020). "In contrast, our data partly show an inverse correlation with age (e-MDSCs on days 3 and 5 after stroke and Arg1 on Mo-MDSCs on day 5)." (PMID 33329318, 2020). "In order to investigate the potential immunosuppressive role of MDSCs after stroke, the transcription factor STAT3p as well as Arg1 were investigated, which are both involved in MDSC-induced T cell suppression." (PMID 33329318, 2020).
Stroke (continued). "Most importantly, MSC graft-associated microglia and infiltrated macrophages were strongly driven towards an Arg-1+ alternative activation status at day 14 after stroke." (PMID 29866203, 2018). "After AIC model selection, ARG1 mRNA expression remained significantly higher in stroke compared to control (p = 0.001), adjusting for sex, diabetes, and prior stroke." (PMID 26515089, 2016). "After AIC model selection, there was a statistically significant association between serum ARG1 protein activity and NIHSS (p = 0.005), adjusted for heart disease and prior stroke." (PMID 26515089, 2016). "Recently, we have been able to demonstrate that intracerebral administration of miR-124 after stroke has led to a clear shift of microglia/macrophages into the anti-inflammatory phenotype, as recognized by the upregulation of the marker Arg-1." (PMID 27539642, 2016). "Similar to ARG1 mRNA, there is a significant relationship between serum ARG1 protein activity and stroke severity, as measured by NIHSS." (PMID 26515089, 2016). "Notably, deletion of Arg1+ microglia promotes neuroinflammation in stroke models, emphasizing the importance of reducing neuroinflammation and balancing microglia activation in recovery." (PMID 38550920, 2024). "This study indicated increased Arg1 expression in macrophages in DNT-treated stroke mice." (PMID 36793857, 2023). "Consistent with histological results, we detected a dramatic upregulation of Arg1 mRNA levels in focal areas after ischemia induction, and the Arg1 levels significantly dropped after MCLs treatment (from 77.73 ± 0.81 in the stroke-MLs group to 25.80 ± 1.67 in the stroke-MCLs group)." (PMID 36361836, 2022). "STAT3p and Arg1 expressions were unchanged early after stroke, suggesting that the MDSCs are at least theoretically able to suppress immune responses as both the phosphorylated transcription factor STAT3 as well as the enzyme Arg1 are essential for anti-inflammatory MDSC function." (PMID 33329318, 2020). "Moreover, the LV-miR-669c injected stroke group had notably increased expression of Arg1 in comparison to LV1-miR-669c injected shams (p = 0.0083)." (PMID 32560730, 2020). "Arginase-1 is not only expressed by resident microglia, but also by infiltrating macrophages post-stroke, suggesting that these cells might be infiltrating M2 macrophages." (PMID 33153476, 2020). "By continuous secretion of IL-13 via MSCs, we could enhance and prolong the expression of neuroprotective and anti-inflammatory marker Arg-1 until week 2 after stroke induction." (PMID 29866203, 2018). "In an earlier study by our laboratory, in which we attempted to modulate the polarization of microglia and macrophages by microRNA-124 after ischemic stroke, we achieved an upregulation of Arg-1 and CD-206 expression by microglia and macrophages until day 6 after stroke." (PMID 29866203, 2018). "We further showed that CD8 expression in the post-stroke brain was associated with activated (CD68+) macrophages and that progressive accumulation of CD8+CD68+ cells in the post-stroke brain coincided with increased iNOS (M1 marker) and reduced Arg1 (M2 marker) expression on these cells." (PMID 29342151, 2018). "Moreover, our results of improved functional outcome are in line with our earlier results, showing an upregulation of the M2-phenotype marker Arg-1 upon early administration of miR-124 after stroke." (PMID 27539642, 2016). "Human stroke genomic biomarker studies have identified a common panel of five genes responding to AIS in the peripheral blood: arginase 1 (ARG1), lymphocyte antigen 96 (LY96), matrix metalloproteinase 9 (MMP9), s100 calcium-binding protein A12 (s100A12), and chemokine CC motif receptor 7 (CCR7)." (PMID 26515089, 2016).